CCL5 (C-C motif chemokine ligand 5)
Diseases named in the same sentence as CCL5 in open-access papers (continued):
Sharing a sentence is not in itself a finding about the gene and the disease.
lupus (24 papers, 2006 to 2025). "A strong positive association between CCL5, ROS generation, and systemic lupus erythematosus had earlier been observed." (PMID 28512644, 2017). "CCL5 plays a critical role in regulating immune cell movement and is indicated to have functions in lupus-associated tissue damage." (PMID 25927578, 2015). "Studies have unveiled the promoted levels of TNF-α and C-C Motif Chemokine Ligand 5 (CCL5) mRNA provoked by TLR4 and TLR7 in spleen macrophages of lupus-susceptible mice." (PMID 32760274, 2020). "Moreover, a transcription factor, Fli1, has been shown to directly bind the promoter region of CCL2 and CCL5 genes to promote their expression in primary endothelial cells of the kidney in NZM2410 lupus-prone mice." (PMID 27403037, 2016). "CCL5 (or RANTES) is one of the many overexpressed chemokines in sera from lupus patients." (PMID 25927578, 2015). "Previous studies have shown that Fli-1 is a positive regulator of CCL2, CCL3, CCL4, CCL5, CXCL9, and CXCL10 in the kidneys of Fli-1 heterozygote knockout mice with lupus and CXCL5 in dermal small vessels from Fli-1 knockout mice." (PMID 40305194, 2025). "We also found that expression of CCL2, CCL3, CCL4, CCL5, CCL8, CCL19, and CXCL10 increased 1.6–5.6-fold in the kidney of lupus-prone MRL.Faslpr mice with advancing age from 9 to 16 weeks." (PMID 37567910, 2023). "We found that expression of CCL2, CCL3, CCL4, CCL5, CCL8, CCL19, and CXCL10 increased 1.6–5.6-fold in the kidney of lupus-prone MRL.Faslpr mice with advancing age from 9 to 16 weeks." (PMID 37567910, 2023). "CCL2, CCL3, CCL5, CXCL10, and CXCL16 are increased in lupus nephritis patients and lupus-prone MRL.Faslpr mice." (PMID 37567910, 2023). "Perhaps the most prominent effect was in its normalization of plasma cytokines, several of which, such as CCL5/RANTES, CXCL2/MIP-2, CXCL12/SDF-1α, and CXCL13/BCA-1, were known biomarkers of lupus severity." (PMID 32582860, 2020). "Upregulation of Axl, Clec7a, Itgax, Ccl5, and Cxcl10 was also observed in NZB/NZW mice, indicating common lupus pathology." (PMID 31888754, 2019). "The chemokines CCL2, CCL3, CCL5, CXCL10, CXCL12, CXCL13, and CX3CL1 are expressed in the nephritic kidney of lupus-prone mice and SLE patients and increase inflammatory cell infiltration into the kidney." (PMID 30057623, 2018). "It is known from animal lupus models and from studies in patients with lupus nephritis that inflammatory chemokines, especially CCL2 and CCL5, were readily detectable in the kidney tissue and urine." (PMID 27852285, 2016). "In addition, multiple chemokines, including CCL2, CCL5, and CXCL10, were expressed at higher levels in PVAT and plasma from lupus mice." (PMID 37006244, 2023). "For example, secretion levels of CCL2, CCL3, CCL4, CCL5, CCL19, CXCL10, and CXCL12 are increased in the kidney of lupus-prone mice and SLE patients during the development of nephritis." (PMID 37567910, 2023). "In human and murine lupus nephritic tissues, enhanced NF-κB activation was also detected, and this could drive the proliferation of mesangial cells (a primary lesion characteristics of lupus nephritis) and expression of a range of chemotactic factors, including CCL2, CCL5, MCP-1, and IL-8, in vitro." (PMID 31546763, 2019). "Recently, we observed that stimulation of primary rat astrocyte cultures with serum or IgG isolated from NMO patients resulted in the release of the potent pro-granulocytic chemokine CCL5, with essentially no release stimulated by serum from MS or systemic lupus erythematosus (SLE) patients." (PMID 26423139, 2015).
AIDS (23 papers, 2013 to 2024). A syndrome resulting from the acquired deficiency of cellular immunity caused by the human immunodeficiency virus (HIV). "The roles of CCL5 in cancer and acquired immune deficiency syndrome (AIDS) have been widely studied." (PMID 38020765, 2023). "Based on the data evaluated, the presence of mutant alleles in the analyzed SNPs—which are associated with increased expression of CCL5/RANTES—seems to confer resistance to AIDS." (PMID 37766364, 2023). "In African-American, European-American, and combined cohorts, infected with HIV-1, the C allele was also shown to reduce CCL5 transcription, increasing the progression rate of AIDS." (PMID 38001676, 2023). "For instance, C allele of the intronic polymorphism rs2280789 in the CCL5 gene has been associated with accelerated progression to AIDS by down regulating CCL5 gene transcription." (PMID 30921390, 2019). "RANTES (CCL5), through promoters 28G-403A, could also slow progression to AIDS, whereas RANTES has another variant, named 1.1.C, which accelerates AIDS development." (PMID 26848682, 2016). "This study suggests that there is an association between the increased expression of CCL5/RANTES and a lower risk of AIDS." (PMID 37766364, 2023). "Some studies have pointed out that CCL5 is a key target for the treatment of AIDS, tumors and even inflammation." (PMID 35345666, 2022). "Even though, clear mechanistic differences between CCL4 and CCL5 interaction with CCR5 are missing, even considering the knowledge gained on CCR5 polymorphisms in HIV/AIDS context." (PMID 34262570, 2021). "Thus, the research conducted so far regarding both gene and protein expression suggests that the elevation of these factors conditioned to CCL5/RANTES appears to mitigate the clinical evolution of general AIDS, and vice versa." (PMID 38674726, 2024). "Increased NK cell activity reflected by higher cytotoxic capacity, IFN-γ and chemokines (CCL3, CCL4, and CCL5) production, has been associated with resistance to HIV infection and delayed AIDS progression, demonstrating the importance of these cells in the antiviral response." (PMID 30386329, 2018). "Numerous preclinical in vitro and in vivo studies have shown a key role of the CCL5/CCR5 axis in cancer, and thus provided the rationale for clinical trials using the repurposed drug maraviroc, a CCR5 antagonist used to treat HIV/AIDS." (PMID 32630699, 2020). "In HIV-positive individuals, the increased cell frequency of memory-like NK cells, virtual memory CD8 T cells, and co-infection with the human T cell lymphotropic virus (HTLV) may elevate the expression of CCL5, playing a role in anti-HIV and delaying AIDS." (PMID 39119185, 2024). "Although the role played by CCL5 in the treatment of HIV/AIDS has recently been reported, our study found no significant change in the CCL5 expression level in patients receiving ART." (PMID 36380676, 2022). "It has been established that the release of CCL5/RANTES plays a critical role in modifying HIV-1 replication in mononuclear phagocytes in the blood and lung, and that the expression of CCR5 on T cell surfaces determines vulnerability to HIV/AIDS through variation in its activation." (PMID 38674726, 2024). "This is in contrast with the predominance of CXCL10 rather than CCL5 in patients with HIV/AIDS during Cryptosporidium infection, and is consistent with the likelihood that the influx of T-cells after C. parvum priming in this model contributed to elevated CCL5." (PMID 27467505, 2016).
depression (23 papers, 2014 to 2026). "These include CXCL1 (Gro-α), CCL2, CCL7 (MCP-1, MCP-3), and CCL5 (RANTES), which have also been implicated in various behavioral impairments including anxiety, depression, and LM." (PMID 29358844, 2017). "Finally, dysregulation of CCL5 has been linked with depression and neuroinflammatory processes in neurodegenerative conditions, such as Alzheimer (AD) and Parkinson’s (PD) diseases." (PMID 33530452, 2021). "In this figure, chemokines (e.g., CX3CL1, CXCL12, CCL5) with direct neurotransmitter-like or neuromodulatory actions may directly influence neurotransmitter systems that are implicated in depression." (PMID 26441528, 2015). "Period Circadian Regulator 2 (Per2)-deficient mice were immune to centrally administered LPS upregulation of CCL5 and thus less likely to suffer from neuroinflammation-induced depression-like behavior." (PMID 36614020, 2022). "A study on pregnant women in the third trimester correlated CCL5 and other chemokines with higher anxiety and anxiety/depression prevalence." (PMID 36614020, 2022). "CCL5, CCL2, and CCL11 were significantly associated with anxiety and depression in a study on the uterine–chemokine–brain axis." (PMID 36614020, 2022). "To assess whether the upregulation of CCL5 occurred in other stressed anxiety/depression models, we measured the CCL5 levels in rats exposed to early life stress (ELS) or chronic unpredictable mild stress (CUMS)." (PMID 37903803, 2023). "Levels of CCL5 are elevated in the serum of patients with depression, suggesting, along with the connection with cognitive impairment and NPSLE, that the decrease of CCL5 in the treatment group may have contributed to the improvement in both behavioral indicators we tested for in this study." (PMID 34868008, 2021). "Positive correlations were observed between MIP-1α/CCL3, MIP-1β/CCL4, MCP-1/CCL2, MIP-3α/CCL20, RANTES/CCL5, Eotaxin/CCL11, and I-TAC/CXCL11 with high scores for anxiety (HARS) (p < 0.05) and for depression (HDRS) (p < 0.004)." (PMID 34863117, 2021). "For this purpose, the correlation between the cytokines VEGF, CCL5, CXCL8 and CXCL10 and BMI, depression, anxiety and stress was assessed while controlling for the neuropathy." (PMID 28811623, 2017). "Evidence also indicates that in patients with major depressive disorder (MDD), levels of inhibitory cytokines (including IL‐4, IL‐10, and IL‐12p70) are decreased, while neurotoxic cytokines (including CCL5) are relatively elevated, and oxidative stress levels are increased." (PMID 41583906, 2026). "Interestingly, this decrease is accompanied by decreased IL-10 and C-C chemokine ligand 5 (CCL5/RANTES) but increased TNF-α in the PFC in a co-model of pain and depression induced by spinal nerve ligation and olfactory bulbectomy model." (PMID 32849076, 2020).
Nephropathy (23 papers, 2011 to 2025). A nonspecific term referring to disease or damage of the kidneys. "Together, these findings indicate that CCL5 deficiency provides a protective effect in ADR-induced nephropathy by reducing albuminuria, glomerular sclerosis, podocyte loss, and foot process effacement, suggesting that CCL5 contributes to the progression of glomerular injury." (PMID 40986444, 2025). "CCL5 deficiency ameliorates ADR-induced nephropathy in mice." (PMID 40986444, 2025). "CCL5 deficiency in BM-derived cells ameliorates ADR-induced nephropathy." (PMID 40986444, 2025). "In this study, we examined CCL5 expression in human glomerular diseases and in a CKD mouse model of adriamycin-induced (ADR-induced) nephropathy, which mimics FSGS — the primary cause of primary glomerular diseases leading to CKD." (PMID 40986444, 2025). "In contrast, mice with CCL5 expression only in BM-derived cells developed the most severe nephropathy, highlighting BM-derived CCL5 as the primary driver of ADR-induced glomerular injury." (PMID 40986444, 2025). "The harmful immune effects of CCL5 in BM-derived cells outweigh its podocyte-protective role, highlighting the importance of cell-targeted strategies to mitigate kidney damage." (PMID 40986444, 2025). "To determine which BM-derived cell type contributes to the deleterious effects of CCL5 in ADR-induced nephropathy, we investigated its role in macrophage polarization." (PMID 40986444, 2025). "In this study, we investigated the role of CCL5 in ADR-induced nephropathy, a widely used CKD model." (PMID 40986444, 2025). "CCL5 in macrophages exacerbates ADR-induced nephropathy by limiting glomerular M2 macrophage accumulation." (PMID 40986444, 2025). "We discovered that CCL5 exerts paradoxical effects in nephropathy; while it protects podocytes in vitro, it exacerbates glomerular injury in vivo." (PMID 40986444, 2025). "To evaluate the in vivo role of CCL5 in ADR-induced nephropathy, we injected WT and Ccl5-KO mice with ADR and then compared the glomerular pathology." (PMID 40986444, 2025). "In summary, this study highlights the dual and context-dependent role of CCL5 in ADR-induced nephropathy." (PMID 40986444, 2025). "A similar pattern was observed in ADR-induced nephropathy mice, where CCL5 was upregulated in podocytes 3 days after ADR injection, showing a capillary pattern colocalized with synaptopodin." (PMID 40986444, 2025). "CCL5 protects kidney-filtering podocytes but worsens nephropathy by driving inflammatory macrophages from bone marrow, highlighting the need for cell-specific therapies in kidney disease." (PMID 40986444, 2025). "CCL5 expression is elevated in multiple kidney diseases, including acute renal failure, HIV nephropathy, transplant rejection, and focal segmental glomerulosclerosis (FSGS)." (PMID 40986444, 2025). "ALPK1 is known to be associated with kidney disease through association studies, and its expression in animal models can regulate the release of the chemokines CCL2 and CCL5 in kidney cells." (PMID 35505381, 2022). "CCL5 was reported to recruit mononuclear cells into injured tissues and some studies have shown that CCL5 dysregulation played a key role in driving the increase and activation of inflammatory macrophages in kidney disease." (PMID 35906541, 2022). "The levels of IL-11 do not increase.Inhibition of IL-18 cannot significantly prevent kidney damage.CCL5 and IL-1α significantly increase.Inhibition of TNF-α can significantly reduce kidney damage.NLRP3 pathway is less important." (PMID 34149721, 2021). "The levels of IL-11 increase.Inhibition of IL-18 can significantly prevent kidney damage.CCL5 and IL-1α slightly increase.Inhibition of TNF-α cannot significantly reduce kidney damage.NLRP3 pathway is the key pathogenesis of inflammation." (PMID 34149721, 2021). "This strategy also reduced kidney damage and the serum elevation of several cytokines and chemokines, except RANTES (CCL5), which was increased after PPK knockdown." (PMID 32867272, 2020).
Nephropathy (continued). "Analysis of the distribution of CD40 and CCL5 mRNA expression by ISH revealed a focal distribution pattern in the kidney cortex in DOX nephropathy similar to that observed in healthy mice receiving the activating CD40 mAb." (PMID 26623936, 2015). "Comparing nephropathy severity across groups, mice with CCL5 expression restricted to kidney-resident cells exhibited the mildest nephropathy, suggesting that CCL5 in kidney-resident cells may play a protective role against ADR-induced nephropathy." (PMID 40986444, 2025). "Given a central role of macrophages in ADR-induced nephropathy, we hypothesized that CCL5 promotes injury by modulating macrophage polarization." (PMID 40986444, 2025). "CCL5 recruits immune cells such as T cells, monocytes, and macrophages to sites of inflammation, exacerbating tissue inflammation and promoting the development of diabetic complications, including nephropathy and retinopathy." (PMID 39807180, 2025). "Additionally, we examined ADR-induced nephropathy in vivo using Ccl5-KO and bone marrow transplant (BMT) models." (PMID 40986444, 2025). "One study identified four Ccl5 gene SNPs that were associated with elevated albumin excretion in non-diabetic patients, which is a prognostic indicator of vascular damage and could lead to nephropathy, a pathological phenomenon driven by CCL5 inflammation." (PMID 32678841, 2020). "Given that these pathways are central to M1 macrophage activation, we propose that in BMDMs, CCL5 activates MAPK and NF-κB signaling via CCR1 and CCR5, leading to sustained M1 polarization and kidney damage." (PMID 40986444, 2025). "While in vitro findings demonstrated that CCL5 protects podocytes from apoptosis, in vivo results revealed that CCL5 exacerbated ADR-induced nephropathy in mice." (PMID 40986444, 2025). "By combining in vitro and in vivo studies, we explored the dual role of CCL5 in podocytes and macrophages, two key cell types involved in ADR-induced nephropathy pathogenesis." (PMID 40986444, 2025). "Immunofluorescence analysis on day 28 after ADR injection revealed CD11b and CD206 colocalization in the glomeruli of both WT and Ccl5-KO mice, as well as in BMT mice, confirming the presence of glomerular M2 macrophages in ADR nephropathy." (PMID 40986444, 2025). "Together, these findings demonstrate that CCL5 is upregulated in podocytes in both human and mouse models of glomerular injury, with its expression in ADR-induced nephropathy following a pattern similar to Notch2 activation." (PMID 40986444, 2025). "To investigate the role of CCL5 in glomerular injury, we analyzed its expression in human kidney biopsies and ADR-induced nephropathy mice." (PMID 40986444, 2025). "CCL5 is significantly upregulated in renal biopsy samples from patients with T2DM and overt nephropathy, and its expression in renal tubular cells has a direct correlation with the interstitial cellular infiltration and the magnitude of proteinuria." (PMID 36726458, 2022). "Given CCL5’s established role in macrophage regulation, we hypothesized that CCL5 exacerbates ADR-induced nephropathy by skewing macrophage polarization toward the proinflammatory M1 phenotype, thereby reducing reparative M2 macrophages." (PMID 40986444, 2025). "Since CCL5 is induced in ADR-treated podocytes, similar to Notch2 activation, we investigated whether CCL5 plays a protective role in ADR-induced nephropathy by assessing podocyte apoptosis." (PMID 40986444, 2025). "Increased expression of RANTES, CC-chemokine ligand 5 (CCL5), has been reported in various kidney disorders and its inhibition might be an important mechanism for treatment of acute kidney injury, renal transplant rejection, and chronic kidney insufficiency." (PMID 27610006, 2016). "Although CCL5 protected in vitro, mice lacking CCL5 experienced less severe ADR-induced nephropathy." (PMID 40986444, 2025).
Nephropathy (continued). "This tissue specificity in T-cell mediated CCL5 to CCR4 interactions was not attributable to the composition of niche cell types in the skin, as T cells were also present in lung, colon and kidney disease interactions." (PMID 40809141, 2024).
pneumonia (23 papers, 2010 to 2025). An acute, acute and chronic, or chronic inflammation focally or diffusely affecting the lung parenchyma, caused by an infection in one or both of the lungs (by bacteria, viruses, fungi, or mycoplasma.). "In fact, these viruses markedly induced the expressions of pro-inflammatory cytokines and chemokines including IL6, IL1α, IL1β, TNFα, IFNγ and CCL5 in the lungs, resulting in severe pneumonia." (PMID 21826229, 2011). "CCL5 blockade has also been shown to produce lethal pneumonia in mice with S. pneumoniae carriage." (PMID 38865072, 2025). "The levels of IFN-γ and RANTES (CCL5) were used as markers of the pneumonia severity in the investigation, and their values were increased in bronchoalveolar lavage fluids (BALF) from the mice, alongside with increased IL-10, whereas viral titers were not affected." (PMID 36293561, 2022). "However, the general downregulation of expression of CCL2, CCL3 and CCL5 in the pneumonia cases may be related to decreases in numbers of peripheral T and B lymphocytes." (PMID 36119044, 2022). "We have shown that CCL5 inhibition resulted in lower IFN-γ-secreting CD4+ T cells and significantly more PspA-specific IL-10-producing CD4+ T cells, which corresponded with the transition from pneumococcal carriage to lethal pneumonia." (PMID 20195541, 2010). "Although the concentrations of IL-13, IL-17A, MIP-1α/CCL3, PAI1, sCD14, IL-1β, CCL11/eotaxin, VEGF/VPF, and RANTES/CCL5 did not exhibit significant differences between the HIV and pneumonia and HIV-only groups, several reasons could explain this lack of disparity." (PMID 38251391, 2024).